IFNG (interferon gamma)
Diseases named in the same sentence as IFNG in open-access papers (continued):
Sharing a sentence is not in itself a finding about the gene and the disease.
tumor (continued). "After stimulation with IFNγ for 24 hours the surface expression of MHC I increased significantly in all four primary tumor cell types." (PMID 26452036, 2015). "Much like with α4-1BB/αCTLA-4 therapy, this combination increased IFNγ and TNFα production in the tumor microenvironment." (PMID 26106583, 2015). "More specifically IFNγ has been shown to directly activate immune cells (i.e. macrophages and NK cells) to reduce tumor growth." (PMID 26497558, 2015). "This suggestion is based on observations cited above that protective immunity to tumours by Th17-like cells is more likely to be achieved if the tumour contains T cells that produce IFNγ." (PMID 26101460, 2015). "IFNγ is typically secreted by activated, tumor-infiltrating cytotoxic T lymphocytes and NK and NK/T cells." (PMID 26654227, 2015). "The splenocytes of mice that cleared tumor secreted significant amounts of IFNγ following stimulation with wild type Neuro2a or Id2kd N2a cells compared to splenocytes taken from naïve mice." (PMID 26079374, 2015). "Other populations of CD8+ cells (i.e., tumor-specific and memory CD8+ T cells) produce high levels of the cytokine interferon gamma (IFN-γ), which is important to the control of tumor metastasis and host survival." (PMID 26695753, 2015). "Initially, IFNγ/STAT1 signaling helps protecting the host from tumor formation and development (immune surveillance), but subsequently IFNγ can also promote the tumors to resist attack (immunoediting) and escape by Darwinian evolution." (PMID 26654227, 2015). "It was later found that although IL-12 induces IFNγ production and counteracts Th2 skewing within the tumor microenvironment, long-term exposure can result in upregulation of Tim-3 and T cell exhaustion, thereby negating any clinical benefit." (PMID 25941795, 2015). "Regression of CD80+ tumors following this immunotherapy regimen was abrogated in IFNγ deficient mice, and 50% of mice who had complete regression of CD80+ tumors rejected tumor transplantation upon re-challenge, firmly establishing an immune mechanism." (PMID 26690220, 2015). "Another example is the programmed death ligand-1 (PD-L1), whose expression on tumor cells is also stimulated by IFNγ and whose engagement with its T cell receptor PD-1 leads to a decrease in T cell proliferation, cytokine production, and T cell adhesion." (PMID 26161423, 2015). "In contrast, the concentration of effector CD8 + T cells in the tumor, IFNG and TNF α were increased by 100 to 1000 times compared to the prediction obtained using the c4 from model calibration." (PMID 26048402, 2015). "The synthetic IFNγ protein inhibits tumor cell growth, invasion and tumor colony formation at a higher efficiency than the unmodified IFNγ." (PMID 26584517, 2015). "To analyze antitumor antigen specific responses, we analyzed the IFNγ production of CD8+ TILs incubated with irradiated Panc02 tumor cells." (PMID 26515728, 2015). "Systemic inflammatory cytokines, such as tumor necrosis factor α (TNFα), interferon γ (IFNγ), and Toll-like receptor 3 ligands, stimulate the expression of a series of intra-tumor chemokines." (PMID 26057470, 2015). "Further, a significantly increased DC and CD8+ T-cell infiltration into the tumor and in the draining lymph nodes was induced, as well as an increased expression of IFNγ by CD8+ T cells." (PMID 25973681, 2015). "Similar functional deficiencies were observed after co-culture with infiltrating CD4+ T cells, including inhibited proliferation and dampened IFNγ and IL-4 production, cytokines that mediate anti-tumor activity." (PMID 25941795, 2015). "A trend towards reduction of tumor growth was observed with non-IFN-gamma pretreated endothelial cells, while a potent reduction of tumor growth was seen in animals treated with cells that were first stimulated with interferon gamma." (PMID 25889119, 2015).
tumor (continued). "Cells were treated with siCtrl or siSUZ12 and left untreated or exposed to physiologically relevant concentrations of IFNγ (0.2 ng/ml), comparable to that secreted by NK cells exposed to tumor cells." (PMID 26030458, 2015). "We can conclude that an MDSC presence affects the number of CD3+IFNγ+ T cells in the tumor microenvironment in vitro." (PMID 25889932, 2015). "Screening strategies before have relied on interferon-gamma (IFN-γ) release as an indicator of anti-tumor NK cell activity." (PMID 25691366, 2015). "In murine models of tumor immunosurveillance, complete elimination of spontaneously arising tumors is possible but depends on several factors, including interferon-gamma, Fas/FasL interactions, perforin, NKG2D, and an intact lymphocyte compartment." (PMID 25992289, 2015). "In contrast, anti-CD28 costimulation favoured an IL-17 phenotype only Furthermore, IFNγ+ Th17 cells developed through costimulation with ICOS ligand were superior to cells costimulated with anti-CD28 in regression of human tumour engrafted into mice." (PMID 26101460, 2015). "A number of human tumor cell lines express IDO1 in a constitutive manner, and most other tumor lines start expressing IDO1 when exposed to IFNγ." (PMID 25691885, 2015). "Cytokines such as IFNγ, which is produced by tumor-infiltrating lymphocytes or NK cells, can also modify the peptide repertoire expressed by tumors." (PMID 26161423, 2015). "In our experiments, there was also an upregulation of IFNγ+ T cells with the tumor growing time in the BMSC-treated tumor-bearing model." (PMID 25889932, 2015). "The inhibition of TGFβ has been shown to directly enhance NK cells, macrophage functions, and T cell activity with the assistance of up-regulation of IFNγ and directly contribute to a T cell mediated inhibition of tumor growth." (PMID 26497558, 2015). "The most notable differences were that ROR1RCD137+ T cells displayed enhanced in vivo tumor clearance despite showing reduced IFNγ production in vitro relative to ROR1RCD28+ T cells." (PMID 26030772, 2015). "The function of ATP is to recruit monocytes and macrophages to the dying tumor cells and stimulate secretion of IL-1β, a key cytokine to polarize interferon-gamma-producing CD8+ T cells." (PMID 25544770, 2015). "Patients with HPV-positive HNSCC have significantly higher levels of tumor-infiltrating CD8+ T cells with the capacity to produce IFNγ and IL-17 after in vitro stimulation." (PMID 25949860, 2015). "Recently, we reported that proinflammatory proteins S100A8/A9 via interaction with RAGE enhanced the activation of NK cells, which produce interferon-gamma (IFN-γ), and significantly suppressed tumor growth." (PMID 26625258, 2015). "Consistent with inhibition of STAT1 activation, Ruxolitinib inhibited IFNγ induction of iNOS expression in the tumor cells." (PMID 26497740, 2015). "Although the majority of solid cancers do not constitutively express MHC II at significant levels and cannot be directly recognized or killed in vitro by CD4+ lymphocytes, many tumour cells can upregulate the MHC II upon stimulation with IFNγ." (PMID 26081906, 2015). "There was a modest positive relationship between the amount of IDO in IFNγ-induced tumor cells and their resistance to combined treatment with these two drugs (R2 = 0.70)." (PMID 26579709, 2015). "Conversely, CD8+ T cells and IFNγ production activated myeloid cells were required for tumor regression." (PMID 26337837, 2015). "PD-L1 expression is either driven by direct oncogenic signaling or upregulated on the tumor cell surface via induction by IFNγ or other inflammatory cytokines, as occurs in the course of the normal immune response." (PMID 26654227, 2015). "Adoptive transfer of T-cells from PV-10 treated mice into sublethally irradiated B16-tumor bearing mice also slowed tumor growth in these animals and T-cells demonstrated increased levels of interferon-gamma (IFN-g) release." (PMID 26618054, 2015).
tumor (continued). "In 2001, it was shown that lymphocytes and IFNγ collaborate to prevent tumor immunoediting, thereby preventing the selection of less immunogenic tumor cells." (PMID 25759690, 2015). "It is worth noting that EI-05 administration also remarkably enhanced the production of IFNγ and Granzyme B by tumor-infiltrated CD8+ T cells." (PMID 25796556, 2015). "Genetic deletions of regions including other immune mediator have been described in some tumors, such as IFNg locus deletions in melanomas, although the relevance of these events in terms of tumor immune architecture is still to be determined." (PMID 26227631, 2015). "We have been interested in elucidating novel functional responses to Ifnγ by tumor cells and primary APECs." (PMID 26029930, 2015). "This production level is far from being insignificant as it corresponds to half of the IFNγ level produced by NK-92CAR after coincubation with the HER2 BT474 tumor cells (9.3 ng/mL and 18.4 ng/mL, resp)." (PMID 26665156, 2015). "An increase in number of CD8+ T-cells and enhanced production of interferon gamma (IFNγ) was observed in tumor antigen stimulated splenocytes of vaccinated mice." (PMID 26079374, 2015). "For spleens from tumor bearing old mice majority of the upstream regulators are either interferons (IFNγ, IFNα, IRF3, IRF7, and IFNA2) or are related to the immune system (IKBKB, CHUK, NFκB, NFκBIA, STAT3, and mir-21) and are predicted to be up-regulated." (PMID 26497558, 2015). "Linked to IFNg producing Th1 cells, CD8+ effector lymphocytes can eliminate tumor cells and help to establish an anti-tumor microenvironment." (PMID 26227631, 2015). "IFN-γ (gene symbol: IFNG) stimulates antitumor immune activity by inhibiting cell proliferation and sensitizes tumor cells to apoptosis." (PMID 25814785, 2015). "According to their report, an ADAM17-specific inhibitor not only rescues FcγRIIIA shedding stimulated by tumor targets but also improves NK cell degranulation as well as IFNγ production in the presence of tumor-specific mAb." (PMID 26284063, 2015). "We observed a trend to an increase in the numbers of total CD4+ T cells as well as IFNγ-producing CD4+ cells (Th1 cells) in the HPV-positive tumor samples (p < 0.1)." (PMID 25949860, 2015). "Specific stimulation of the coreceptor ICOS was reported to be capable of skewing Th17 cells to become IFNγ/IL-17-producing cells which have been revealed to be beneficial for tumour suppression." (PMID 26101460, 2015). "This is the case for instance of the programed death ligand 1 (PDL1) up regulation on tumor cells upon local IFNg production by infiltrating lymphocytes." (PMID 26227631, 2015). "The notion that coexpression of IFNγ and IL-17 is favourable for tumour immunity was supported by another study of ovarian cancers." (PMID 26101460, 2015). "On the other hand, P-PA/ODN induced only a 50% higher IFNγ, which is a critical mediator of anti-viral response and is extensively involved in anti-tumor response, than CpG ODN alone." (PMID 26577983, 2015). "To examine the capacity of Tim-3-PD-1-, Tim-3-PD-1+ and Tim-3+PD-1+ tumor-infiltrating T cells to produce IFNγ, we analyzed the phenotype of these cells after in vitro stimulation with PMA and ionomycin using flow cytometry." (PMID 25949860, 2015). "In humans, the major cytokine produced by γδT cells is IFNγ, contributing to its role in anti-viral, anti-bacterial, and anti-tumor immunity." (PMID 25699053, 2015). "The ability to shrink tumours was dependent on this antigen presentation to Th17 cells and the cells also gaining the ability to produce IFNγ." (PMID 26101460, 2015). "We determined that IFNγ and NF-κB synergistically induce iNOS expression in both tumor cells and myeloid cells." (PMID 26497740, 2015). "Interferon gamma and other inflammatory cytokines, secreted by anti-tumor TH1-cells or macrophages, increase PDL1 expression, in response to immune-mediated attack, to decrease the cytotoxic local immune response." (PMID 25940795, 2015).
tumor (continued). "Mice over-expressing IL-23 were found to secrete large amounts of IFNγ, suggesting the involvement of T-cells, leading to systemic anti-tumour immunity." (PMID 25015728, 2014). "These CD4+ T-cells would have likely produced Th1 cytokines, like IFNγ and IL-2, stimulating X5563-specific effector T-cell clones already present in the animal allowing for cytotoxic responses to the tumor." (PMID 24949488, 2014). "These authors suggested that B cells are required for optimal CD4+ and CD8+ T cell tumor immunity, noting that effector-memory and IFNγ– or TNFα–secreting CD4+ and CD8+ T cell induction was significantly impaired in B cell-depleted mice with tumors." (PMID 24498358, 2014). "They resembled effector memory αβT (TEM) cells and retained full functionality as assessed by in vitro tumor cell killing as well as secretion of pro-inflammatory cytokines (IFNγ, TNFα) and cell proliferation in response to stimulation with phosphoantigens." (PMID 25101086, 2014). "Addition of interferon-gamma sensitized COX-2 expressing cancer cells to tumor suppression by antigen-specific T cells." (PMID 25501829, 2014). "It should be made clear that multiple pathways besides IFNγ activated JAK/STAT signaling can affect PD-L1 expression in tumor cells." (PMID 24551119, 2014). "Functional T cells are detected using optimised interferon gamma capture following stimulation with viral or tumour cell-derived antigen." (PMID 25368986, 2014). "Interferon-gamma (IFN-γ) is a glycoprotein generated by lymphocytes that possesses anti-tumor, antiviral and immunomodulatory functions." (PMID 24849390, 2014). "Naïve CD4+ T cells in Id-specific TCR-transgenic mice, which eradicate injected MHC IINEG tumor cells, develop into IFNγ-secreting Th1 TILs that induce macrophage polarization into tumoricidal M1 macrophages." (PMID 24782871, 2014). "Efficacious anti-tumor therapeutic or vaccine approaches tested in murine models resulting in protection from tumors are characterized by strong Th1 polarization, M1 macrophage activation, a TNFα response, and an anti-tumor IFNγ-producing CD8+ CTL." (PMID 25072019, 2014). "iNKT-cells, activated by CD1d presentation of haptenated tumor glycolipids, and γδ T-cells will work together to produce IFNγ, which has an antitumor protective role as a potent Th1 cytokine and mediates antitumor activity." (PMID 24949488, 2014). "IFNγ ELISPOT assay was used to assess T cell IFNγ secretion from splenocytes of treated mice 12 days post tumor implantation." (PMID 24806510, 2014). "The vaccine, ISCOM+TLR9+OVA antigen, was able to induce strong immunity against the tumor and induce effective memory responses, including a high percentage of CD8+IFNγ+ T cells after re-induction of the tumor." (PMID 26344621, 2014). "IFNγ also stimulates the host immune response and enhances tumor cell apoptosis via tumor necrosis factor (TNF)-related apoptosis-inducing ligand (TRAIL)." (PMID 25428727, 2014). "The cells were co-cultured with different tumor lines and analyzed for IFNγ and IL-2 secretion as well as activation marker upregulation." (PMID 25431955, 2014). "Taken together, these results are consistent with the view that activated NK cells play a role in controlling the early phase of tumor metastasis in the lungs and suggest a role for IFNγ and/or perforin during VSV-induced reduction of metastasis." (PMID 24498205, 2014). "Knowing that IFNγ and perforin play an important role in NK-mediated tumor control, we next sought to investigate the role of these mediators in tumor control during the early phase of lung metastasis." (PMID 24498205, 2014). "IFNγ then send signals via STAT1 to increase anti-tumor responses through the activation of natural killer cells, macrophages and CD8+ T cell-mediated cytolytic activity." (PMID 25076205, 2014). "IFNG is a soluble cytokine, predominantly produced by the NK cells with antiviral, immunoregulatory, and anti-tumor properties." (PMID 25928531, 2014).
tumor (continued). "This treatment markedly inhibited tumor growth, and was accompanied by massive infiltration of IFNγ-producing T cells." (PMID 24416401, 2014). "We have reported that tumor cells that are resistant to FasL-mediated apoptosis can be sensitized following treatment with interferon-gamma (IFN-γ)." (PMID 25053986, 2014). "We have already shown Delta-24-RGD injection increases T-bet expressing cells within the tumor, which should result in the upregulation of Th1 cytokines including IFNγ." (PMID 24827739, 2014). "Natural killer (NK) cells eliminate virus-infected and tumor cells through the release of perforins and granzymes; they also produce Interferon gamma (IFN-γ) and Tumor necrosis factor alpha (TNF-α), which induce apoptosis in target cells." (PMID 25302050, 2014). "The increased production of IFNγ in the tumor and spleen of WT mice treated with RT + anti-CTLA-4 in the presence of CD1d blockade supports this interpretation." (PMID 25349699, 2014). "We noted a significantly increased infiltration of CD8+ cells, while the CD4+ and IL2+ cell count in the tumor environment of IFNγ-ADSC treated mice remained constant." (PMID 25428727, 2014). "To evaluate the role of IFNγ in the anti-tumor effect of the combination treatment of CY+1D11, we examined its effect in 4T1 tumor-bearing IFNγ KO mice." (PMID 24416401, 2014). "First, we assessed the level of the MHC class I and APM molecule expression and its modulation by IFNγ on the selected tumour cells." (PMID 25071011, 2014). "In inflammation-induced cancers, the Hedgehog signaling pathway mediates IFNγ-induced tumor development." (PMID 24069395, 2013). "A recent study demonstrated that antibodies against CTLA-4 (anti-CTLA-4) induce proliferation of TCR stimulated T effector cells and abrogate Treg suppressive activity by enhancing IL-2 and IFNγ release in response to polyclonal or tumor antigen stimulation." (PMID 23861693, 2013). "Unlike T cells and B cells, NK cells can exert direct cellular cytotoxicity on tumor cells without prior sensitization and secrete immunostimulatory cytokines like interferon gamma (IFN-γ), which controls both local tumor growth and metastasis." (PMID 23409093, 2013). "IRAK-M−/− BMDCs secrete increased levels of TH1 cytokines such as IFNγ, and skew the T cell response in vivotowards a more proinflammatory phenotype to prolong survival in a tumor vaccine model." (PMID 23776703, 2013). "On the other hand, endogenous IL-17 has been shown to reduce tumor growth and lung metastasis due to the effects of IFNγ + NK and IFNγ + tumor-specific T cells; these results suggest that IL-17 potentially promotes protective tumor immunity." (PMID 23379788, 2013). "IFNγ has been shown to inhibit tumor growth, and we found both IFNγ and MIG, a monokine-induced by IFNγ, at lower levels in the plasma of patients with MM." (PMID 23544044, 2013). "Together, these results demonstrate that irradiation followed by lymphocyte infusion augments the frequency of vaccine-generated tumor antigen specific, IFNγ-producing CD8+ T cells." (PMID 24349298, 2013). "To define the immune mechanism and evaluate the immunologic efficacy of Lm-LLO-E7/anti-PD-1 Ab combination we next assessed the levels of antigen-specific IFNγ-producing cells in spleens from treated tumor-bearing mice and tumor-infiltrated CD8 T cells." (PMID 24829751, 2013). "IFNG inhibits proliferation, sensitizes tumor cells to apoptosis, up regulates MHC class I and class II expression, and stimulates antitumor immune activity." (PMID 24244422, 2013). "Rejection is mainly dependent on cytotoxic T lymphocytes (CTL) and IFNγ, although a role for NK cells and dendritic cells has been observed in some tumor models." (PMID 24764534, 2013). "The Th17 cells showed a survival advantage over other transferred T-cells, and the anti-tumor immune response appeared to be dependent on IFNγ production." (PMID 26344346, 2013).